RB1 (RB transcriptional corepressor 1)
Diseases named in the same sentence as RB1 in open-access papers (continued):
Sharing a sentence is not in itself a finding about the gene and the disease.
retinoblastoma (continued). "The loss of RB1 function drives tumorigenesis in limited types of malignancies including retinoblastoma and small cell lung cancer." (PMID 34359636, 2021). "Retinoblastoma occurs when both alleles of the RB1 gene, which is a tumor suppressor gene located at chromosome 13q14, are mutated." (PMID 34195690, 2021). "Retinoblastoma (RB) is an ocular tumor of the pediatric age caused by biallelic inactivation of the RB1 gene (13q14)." (PMID 34573300, 2021). "At least one RB1 mutation was identified in all retinoblastomas, including new mutations in addition to those previously identified by clinical screening." (PMID 33670346, 2021). "Due to autosomal dominant inheritance and high penetrance of the inherited RB1 mutation, offspring who carry the familial mutation have a highly increased risk of developing retinoblastoma." (PMID 33920538, 2021). "In particular, it has been shown that approximately 15% of sporadic retinoblastoma cases are caused by postzygotic RB1 mutations, that intrafamilial phenotypic variability in aniridia cases can be explained by PAX6 mosaicism." (PMID 33420188, 2021). "Beyond RB1, the only recurrently mutated gene in retinoblastoma (7–13% of cases) is the epigenetic modifier gene BCOR19–21." (PMID 34552068, 2021). "Retinoblastoma (Rb) is a malignant neoplasm arising during retinal development from mutations in the RB1 gene." (PMID 34003213, 2021). "According to published data, low-penetrance RB1 mutations inherited from the father more often cause retinoblastoma and determine its more severe form than the same mutations inherited from the mother." (PMID 34680218, 2021). "RB1 gene was thought to be mechanistically involved in the initiation of retinoblastoma as its inactivation following genetic mutation or deletion was prevalently identified in the pedigrees of hereditary cases." (PMID 34359636, 2021). "Our aim was to identify RB1 alterations causing hereditary low penetrance retinoblastoma and to evaluate how the parental origin of an RB1 mutation affects its phenotypic expression." (PMID 34680218, 2021). "Especially children with somatic mosaicism of RB1 variant presented with a higher age at diagnosis in the group of children with heritable retinoblastoma." (PMID 33919815, 2021). "Our results support an assumption that parental origin of an RB1 mutation influences the likelihood of developing retinoblastoma." (PMID 34680218, 2021). "Two Rb tumors each characterized by two pathogenic RB1 mutations were dissociated to single cells and subjected to scRNA-Seq and scATAC-Seq using the 10× Genomics platform." (PMID 34003213, 2021). "A significantly increased risk of SPM has been observed in survivors of hereditary retinoblastoma with high RB1 mutations." (PMID 33446816, 2021). "We aim to analyze the characteristics of RB1 gene pathogenic variant and clinical phenotype in retinoblastoma patients and their relatives." (PMID 34336010, 2021). "Ophthalmological screening is crucial in children with a proven inherited RB1 mutation and all offspring in families where the causative retinoblastoma mutation cannot be detected, hereafter named at-risk children." (PMID 33920538, 2021). "Retinoblastoma is the most common intraocular malignancy in children, which forms when both RB1 alleles have been mutated in a susceptible developing retinal cell, leading to an inactivation of the retinoblastoma tumor suppressor." (PMID 33920538, 2021). "The RB1 tumor suppressor is recurrently mutated in a variety of cancers including retinoblastomas, small cell lung cancers, triple-negative breast cancers, prostate cancers, and osteosarcomas." (PMID 33591981, 2021). "The identification of low-penetrance mutations in the RB1 gene and the study of their inheritance in pedigrees is contributing to understanding the mechanisms underlying the development of retinoblastoma with low penetrance." (PMID 34680218, 2021).
retinoblastoma (continued). "For example, it was shown that inactivation of both alleles of RB1 leads first to retinoma, a benign tumour with genomic instability that easily transforms to retinoblastoma upon acquiring additional mutations." (PMID 34434669, 2021). "Retinoblastoma (RB) is an aggressive retinal cancer that is initiated in response to biallelic loss of the tumor suppressor gene RB1 in almost all cases and develops after additional genetic/epigenetic alterations." (PMID 34512157, 2021). "Efficacy of RB1 mutation screening in blood samples depends on the clinical form of retinoblastoma (unilateral or bilateral) and on the family history (inherited or sporadic disease)." (PMID 34680218, 2021). "The age of diagnosis was 40.7 months for PD34256 and 38.3 months for PD37495, compared with a mean age of diagnosis of retinoblastoma tumours with somatic RB1 mutations of 34.32 ± 16.42 months, (95% CI 41.88, 26.72)." (PMID 33670346, 2021). "Patients with 13q-syndrome are at risk of retinoblastoma when the RB1 gene, located in the chromosomal band 13q14.2, is deleted." (PMID 34479642, 2021). "While retinoblastoma initiation is triggered by the inactivation of both alleles of the retinoblastoma tumor suppressor gene (RB1) in the developing retina, tumor progression requires additional epigenetic changes, retinoblastoma genomes being quite stable." (PMID 33953844, 2021). "Heritable retinoblastoma is a rare autosomal dominant tumor predisposition syndrome caused by constitutional haploinsufficiency of the RB1 gene." (PMID 33807189, 2021). "In general, over 10% of patients with sporadic unilateral retinoblastoma have a germline RB1 mutation." (PMID 33917779, 2021). "RB1 is a tumor suppressor gene that is frequently mutated in various tumors, including retinoblastomas, small cell lung cancers, triple-negative breast cancers, prostate cancers, and osteosarcomas." (PMID 33591981, 2021). "Loss or inactivation of both copies of RB1 results in initiation of retinoblastoma tumors; however, additional genetic changes are needed for the continued growth and spread of the tumor." (PMID 34003213, 2021). "Almost half of retinoblastoma patients have the heritable variant of disease, where subjects carry a germline RB1 mutation, which can either arise de novo (sporadic) or is inherited from a parent." (PMID 33920538, 2021). "Constitutional haploinsufficiency of the RB1 gene causes heritable retinoblastoma, a tumor predisposition syndrome." (PMID 33807189, 2021). "Most patients with heritable retinoblastoma are heterozygous for variant alleles that create premature termination codons (PTCs) in regions of the RB1 gene where PTCs are expected to cause nonsense-mediated decay (NMD)." (PMID 33807189, 2021). "Alterations in additional pathways contribute further to RB1 mutations and drive retinoblastoma initiation and progression by activating oncogenes and suppressing tumor suppressors." (PMID 34680394, 2021). "RMS, especially ERMS, is occasionally detected as one such secondary neoplasm in individuals with RB1 mutations that have completed retinoblastoma treatment." (PMID 34065162, 2021). "Over 99% of retinoblastomas are due to the inactivation of the RB1 tumour suppressor gene, caused by either two somatic mutations or an initial germline mutation followed by a subsequent somatic hit." (PMID 33805427, 2021). "The hereditary retinoblastoma phenotype is thought to depend on the type of the germline (first) mutation affecting one of the RB1 alleles." (PMID 34680218, 2021). "Mild intellectual disability, growth delay, limb malformations, and retinoblastoma risk (when the RB1 gene is deleted [chromosomal position 13q14.2]." (PMID 34479642, 2021).
retinoblastoma (continued). "Loss of both copies of the retinoblastoma (RB1) gene on chromosome 13q 14 is thought to be the most common cause of retinoblastoma." (PMID 34639028, 2021). "The somatic profiles of tumours from different eyes of bilateral retinoblastoma patients have been found to be discordant, both in terms of the second somatic RB1 pathogenic variant and non-RB1 secondary events." (PMID 33805427, 2021). "Such efficacy of RB1 germline mutation screening in an overall cohort of retinoblastoma patients is consistent with previous reports." (PMID 34680218, 2021). "Retinoblastoma is a rare retinal tumour that is primarily diagnosed during early childhood and is most commonly caused by mutations in the RB1 tumour suppressor gene." (PMID 33473166, 2021). "We used whole-genome sequencing (WGS) and transcriptomics to investigate the landscape of sporadic retinoblastomas derived from twenty patients, sought RB1 and other driver mutations and investigated mutational signatures." (PMID 33670346, 2021). "In 2019, we also reported on cfDNA analysis in retinoblastoma and, for the first time, described the detection of somatic RB1 pathogenic variants in aqueous humour." (PMID 33805427, 2021). "RB1-deficient human retinoblastoma cells undergo apoptosis after Skp2 knockdown via the activation of p27." (PMID 33591981, 2021). "Conversely, early diagnosis and treatment of retinoblastoma in developed countries were associated with a surge in RB1 gene carriers." (PMID 34790455, 2021). "Retinoblastoma, a childhood cancer of the eye, is thought to be caused by inactivating mutations of both copies of the RB1 gene." (PMID 33670346, 2021). "Previous cytogenetic analyses have shown RB1 loss in lipoma, providing support for an association between germline RB1 mutations in hereditary retinoblastoma and a high incidence of lipoma in these survivors." (PMID 33917779, 2021). "The power of whole-genome sequencing to identify RB1 mutations of all mutation types can have significant relevance to the clinical management of retinoblastoma patients and genetic counselling of their families." (PMID 33670346, 2021). "Yet, such an approach is sufficient to address the key question of the study, assessment of the parental origin of the RB1 gene mutations in families with low penetrance hereditary retinoblastoma." (PMID 34680218, 2021). "Retinoblastoma (Rb) is a childhood cancer of the developing retina caused by biallelic inactivation of RB1 or MYCN amplification in a susceptible retinal cell type." (PMID 34003213, 2021). "Intriguingly, a recent functional genomics screen identified HRd as selectively lethal in cell lines derived from retinoblastoma, a tumour primarily initiated by RB1 loss." (PMID 34862364, 2021). "Patients with hereditary retinoblastoma carry a germline mutation in the RB1 gene and are at substantially increased risk of subsequent malignant neoplasms (SMNs) compared to patients with nonhereditary retinoblastoma and to the general population." (PMID 33917779, 2021). "RB1-deficient human retinoblastoma cells underwent apoptosis after Skp2 knockdown and small molecule inhibitors of SKP2 were SL in RB1 defective triple negative breast tumor cells." (PMID 33591981, 2021). "A multi-step model for the progression of normal retina to retinoblastoma has been proposed, the first step being the inactivation of both alleles of the tumor suppressor gene RB1 in the developing retina." (PMID 33953844, 2021). "It was originally believed that profound amplification of MYCN (≥10 copies) was only associated with a small subset of retinoblastomas that lack detectable RB1 mutations." (PMID 33670346, 2021). "Children with germline mutations in RB1 have a high likelihood of developing retinoblastoma and other malignancies later in life." (PMID 34315877, 2021).
retinoblastoma (continued). "In our series, all three patients with germline mutations in the RB1 gene presenting with intraocular retinoblastoma followed by extraocular relapse after failing conservative therapy (group 2) had 11q deletion." (PMID 33567541, 2021). "This particular phenotype distribution within families, which is often referred to as low-penetrance retinoblastoma, is associated with a subset of pathogenic RB1 variants." (PMID 33807189, 2021). "The spectrum of pathogenic RB1 variants is very broad, as reflected in our retrospective study cohort comprising children diagnosed with heritable retinoblastoma between 1992–2011 and in other national cohorts." (PMID 33807189, 2021). "Heritable retinoblastoma is a tumor predisposition syndrome caused by a constitutional pathogenic RB1 variant." (PMID 33919815, 2021). "The development of retinoblastoma is thought to require pathological genetic changes in both alleles of the RB1 gene." (PMID 33670346, 2021). "The major cause of retinoblastoma was originally thought to be a consequence of mutations on both RB1 alleles." (PMID 34639028, 2021). "Retinoblastoma (RB) is a childhood cancer of the retina that is usually caused by inactivation of the biallelic gene of the RB1 tumor suppressor gene." (PMID 32509443, 2020). "Approximately half of retinoblastoma patients carry a mutation in the RB1 gene in their constitutional cells." (PMID 32113195, 2020). "RB1 deficiency makes the retinoblastoma cell-of-origin extremely susceptible to cancerous transformation, and the tumor cell-of-origin appears to depend on the developmental stage and species." (PMID 32824373, 2020). "–5 This oncogene-driven retinoblastoma type is a very early-onset unilateral tumor that exhibits more aggression than the classical RB1-deficient retinoblastoma." (PMID 33270844, 2020). "In this proof of concept study, we demonstrate the feasibility of detecting somatic RB1 mutations in plasma cfDNA of patients with retinoblastoma." (PMID 32633890, 2020). "Retinoblastoma is the most common childhood intraocular malignancy caused by bi-allelic inactivation of the retinoblastoma gene (RB1)." (PMID 32426419, 2020). "A third report indicated a total deletion of exons 1–27 of BRCA2 and exons 1–27 of RB1 indicating increased risk of breast cancer and retinoblastoma, respectively." (PMID 32377377, 2020). "Mutations in the RB1 gene are found in retinoblastoma, osteosarcoma, and small cell lung cancer at a high frequency, and with less frequency in other types of cancer." (PMID 33003565, 2020). "Children with interstitial chromosome 13q deletions that include the RB1 gene show a predisposition to develop retinoblastoma and variable other features." (PMID 32760450, 2020). "Compared with the general population, Rb1 gene inactivation mutation increases the risk of retinoblastoma (usually in the eyes) by 10,000 times." (PMID 32532965, 2020). "The proliferative cells of RB170 differed from those of RB1-deficient retinoblastoma, where M/L opsin is primarily expressed." (PMID 33270844, 2020). "MR Imaging is recommended for (suspected) retinoblastoma to assess disease extent, estimate metastatic risk and to screen the CNS for metastasis or RB1 mutation associated with intracranial neuroectodermal tumors (trilateral retinoblastoma)." (PMID 33266342, 2020). "More studies are needed to determine the potential association of Eag1 expression with prognosis, mutations in RB1, or response to chemotherapy in retinoblastoma." (PMID 31973216, 2020). "Retinoblastoma is a retinal cancer that is initiated in response to biallelic loss of RB1 in almost all cases, together with other genetic/epigenetic changes culminating in the development of cancer." (PMID 32824373, 2020). "A copy number of MYCN greater than 28 is considered high amplification and is associated with RB1+/+ or RB1+/− retinoblastoma." (PMID 32824373, 2020).
retinoblastoma (continued). "In conclusion, this study demonstrates the feasibility of using plasma cfDNA to obtain a molecular profile of retinoblastoma by determining the key mutations in the RB1 gene." (PMID 32633890, 2020). "In heritable retinoblastoma cases, the initial hit to the RB1 gene occurs at the germline level and the second mutation occurs in a retinal cell at the somatic level leading to tumor formation." (PMID 32633890, 2020). "Of the 75 patients carrying RB1 mutations, 56 developed bilateral Rb, while 19 developed unilateral Rb." (PMID 32218800, 2020). "Studies have examined small genetic lesions by exon sequencing and revealed that mutations beyond RB1 are rare in retinoblastoma." (PMID 32824373, 2020). "Biallelic mutations of the RB1 tumor suppressor gene are seen in both heritable and non‐heritable forms of retinoblastoma." (PMID 32633890, 2020). "This reduces access to tumor tissue for molecular profiling, especially in unilateral retinoblastoma, and hinders the confirmation of somatic RB1 mutations necessary for genetic counseling." (PMID 32633890, 2020). "In humans, Retinoblastoma susceptibility gene is a member of a small gene family that includes RB1 (p105/pRb), RBl1 (p107/pRBL1), and RBl2 (p130/pRBL2), whose protein structure are very similar, and that share some overlapping functions." (PMID 32664691, 2020). "Retinoblastoma is a rare intraocular malignancy and typically initiated by inactivating biallelic mutations of RB1 gene." (PMID 33225895, 2020). "Retinoblastoma develops due to germline or somatic mutations of both alleles of the RB1 gene which is recognized as a tumour suppressor gene." (PMID 32047660, 2020). "The results from this proof of concept study should be further evaluated in large cohorts that involve all stages of retinoblastoma patients, using a fully validated assay to further improve the accuracy of detecting low‐level RB1 mutation in plasma DNA." (PMID 32633890, 2020). "Most bilateral tumors are caused by germline mutations in the RB1 gene whereas the majority of unilateral retinoblastomas are associated with the presence of somatic RB1 mutations." (PMID 33575207, 2020). "Retinoblastoma initiation occurs with exceptionally high efficiency in response to the loss of functional pRB protein, which is encoded by the RB1 gene." (PMID 33090698, 2020). "For example, in the 7 patients with unilateral retinoblastoma, we detected the RB1 mutations from cfDNA in 6 of 7 samples, except sample P19 despite a unique coverage of 1596x." (PMID 32633890, 2020). "The inciting factor leading to development of retinoblastoma is a loss of function mutation in the RB1 gene on chromosome 13, the first described tumor suppressor." (PMID 32633890, 2020). "This somatic mutation identified in the cfDNA is likely the second hit to the RB1 gene that are associated with the development of bilateral retinoblastoma." (PMID 32633890, 2020). "Loss of function of the retinoblastoma gene (RB1) is the rate-limiting step in the initiation of both the hereditary and sporadic forms of retinoblastoma tumor." (PMID 33003565, 2020). "Identification and classification of the RB1 mutation is important for clinical decision making in treatment of retinoblastoma and providing guidance to the patients and their families." (PMID 32633890, 2020). "As it is known that advanced tumors shed more tumor derived cfDNA27, 37; future studies are needed to determine the feasibility to detect somatic RB1 mutations from cfDNA in patients with earlier stages of retinoblastoma." (PMID 32633890, 2020). "The primary symptom of germline mutations (autosomal dominant) in the RB1 gene is childhood retinoblastomas; however, in later life there is an increased risk of various neoplasms, especially OS." (PMID 32751922, 2020).